EGFR (epidermal growth factor receptor)
Diseases named in the same sentence as EGFR in open-access papers (continued):
Sharing a sentence is not in itself a finding about the gene and the disease.
breast carcinoma (continued). "EGFR is overexpressed in many solid tumors including breast cancer and is associated with increased cell growth, angiogenesis, and blocking of cell death." (PMID 32349284, 2020). "TNBC is associated with worse outcomes compared to other breast cancer subtypes, and EGFR overexpression is common in this disease subtype, supporting the potential utility of therapies that target this receptor tyrosine kinase." (PMID 32552913, 2020). "Both molecules are associated with an inhibition of the growth of breast cancer MDA-MB-231 cells by disrupting the positive regulatory loop with epidermal growth factor receptor (EGFR), which promotes malignant growth of TNBC cells." (PMID 32526980, 2020). "The regulation of IGF transport and uptake by IGFBPs has been proven to be associated with the occurrence of breast cancer by activating the EGFR and IGFR signaling pathways." (PMID 33138076, 2020). "Breast cancer that expresses epidermal growth factor receptors (EGFR) is associated with poor patient prognosis, both in TNBC and in non-TNBC subtypes." (PMID 31936350, 2020). "TNK2 (also known as ACK1) associates with EGFR in cancer cells to maintain EGFR on the cell surface and enhance human breast cancer cell migration and invasion." (PMID 33213062, 2020). "In order to investigate if EGFR-pathway dysregulation occurs in specific subgroups of breast cancer patients, associations between elevated S-EGFR and decreased S-EGF and clinicopathological characteristics were evaluated." (PMID 32317675, 2020). "We detail the clinical prognostic significance of a positive association between resistin and EGFR expression in breast cancer." (PMID 33313320, 2020). "Suppression of ErbB2 breast tumors by MEDICA in ErbB2/neu mouse transgenes as well as in human ErbB2 breast cancer cells was accompanied by loss of plasma membrane ErbB2, together with other ErbB family members, including EGFR (ErbB1) and ErbB3." (PMID 32695336, 2020). "Therapies that place significant selective pressure (eg, hormonal therapy for prostate and breast cancer; EGFR inhibitors in EGFR-mutated NSCLC) do produce clear, pathway-convergent resistance mutations." (PMID 33048619, 2020). "We have previously demonstrated that TRPV4 expression is also associated with a breast cancer gene cluster (referred to as Red Module) that is strongly associated with EGFR, a gene often involved in the EMT process." (PMID 33322037, 2020). "In particular, co-expression of human epidermal growth factor receptor 2 (HER2) and EGFR has been reported to be associated with worse survival in HER2-positive breast cancer patients." (PMID 32942617, 2020). "In a retrospective study conducted by our group, SIAH alone or in combination with EGFR had better prognostic value in high-risk breast cancer, outperforming ER, PR, HER2, and Ki67, as a new biomarker." (PMID 32542231, 2020). "As the previous reports, OTUD7B regulated deubiquitination and endocytosis of EGFR associated with breast cancer proliferation, migration and malignancy." (PMID 31747939, 2019). "Dysregulation of epidermal growth factor receptor (EGFR)/human epidermal growth factor-2 (HER2) family is a hallmark of aggressive breast cancer." (PMID 30781364, 2019).
breast carcinoma (continued). "The EVs released from the engineered HEK293 cells were used to efficiently deliver the let-7a miRNA to EGFR+ breast cancer cells, causing tumor growth inhibition." (PMID 30991632, 2019). "EGFR is composed of ErbB1, ErbB2, ErbB3 and ErbB4 proteins, an increase in the overexpression of ErbB proteins has been linked to the development of breast cancer." (PMID 30769862, 2019). "Clinically, more than 20% of breast cancer patients are diagnosed with positive human epidermal growth factor receptor (EGFR), which is associated with a reduced survival rate of breast cancer." (PMID 31772931, 2019). "Stromal PD-L1 status was also associated with different breast cancer subtypes and EGFR expression level." (PMID 31584964, 2019). "The most frequently observed mutations occurred within the coding region of PIK3CA (6 out of 18 mutations detected) for breast cancer and EGFR (40 out of 57 mutations detected) for NSCLC specimens." (PMID 31296838, 2019). "EMT-associated markers EGFR, EpCAM, fibronectin and vimentin were also evaluated using immunofluorescence for the six breast cancer cell lines." (PMID 31430931, 2019). "ACK1 enhances cancer-causing epidermal growth factor (EGFR) signaling and has been shown to increase proliferation and invasiveness of breast cancer cells." (PMID 31772931, 2019). "EGFR is one of the receptors that has been associated with the progression of breast cancer and the overexpression of the EGFR is often associated with poor prognosis." (PMID 31064156, 2019). "The primary role of DNAJC13 is in early endosome transportation, and in ERBB2 positive breast cancers has been implicated in the trafficking of epidermal growth factor receptor (EGFR) to the plasma membrane." (PMID 30578123, 2019). "HER2 is amplified in about 20% of all breast cancer patients and is a member of the same receptor tyrosine kinase family as EGFR which is known to be mutated in 15% of patients with lung ADC." (PMID 31083571, 2019). "Meanwhile, stromal PD-L1 expression status was implicated with ER status, PR status, EGFR expression level and different molecular subtypes of breast cancer." (PMID 31584964, 2019). "Previous studies have shown the Epiregulin (EGFR) ligands have the effect of stabilizing receptors, affecting breast cancer cells associated with differentiation function." (PMID 31001929, 2019). "We searched GEO database to obtain gene signatures associated with lung/breast cancer and acquired resistance to EGFR TKIs/tamoxifen to query CMap." (PMID 31993373, 2019). "c-Src-mediated phosphorylation of EGFR at Tyr845, Tyr992, and Tyr1086 is associated with resistance to anti-EGFR therapy in breast cancer." (PMID 29455658, 2018). "A high-content siRNA screen identified the endosomal sorting complexes required for transport (ESCRT)-associated protein ALIX as a regulator of both EGFR activity and PD-L1 surface presentation in basal-like breast cancer (BLBC) cells." (PMID 30021161, 2018). "Efficacy of molecular-targeted medicine for cancers with driver oncogenes, such as HER-2 amplification in breast cancer, EGFR mutation and ALK-rearrangement in NSCLC, and BRAF mutation in malignant melanoma, is found to be very high." (PMID 30443294, 2018). "show that the ESCRT-related protein ALIX regulates two clinically important proteins in breast cancer; namely, EGFR, a receptor linked to cell survival, and PD-L1, an immune checkpoint protein." (PMID 30021161, 2018). "Since EGFR is well-established as being up-regulated/over expressed in breast cancers with amplification and mutations especially prevalent in >60% of TNBC cases, it is one possibility for the increased toxicity observed in TNBC cells versus the normal cells." (PMID 30373175, 2018). "Activation of c-Met during EGFR treatment facilitates c-Src kinase-associated phosphorylation and cell growth in breast cancer cells." (PMID 29455658, 2018).
breast carcinoma (continued). "The authors added that the adoption of this technology in hospitals has already improved the manner in which healthcare practitioners detect and monitor KRAS, BRAF, and EGFR mutations in patients with lung, colon, and breast cancer, respectively." (PMID 29728089, 2018). "Using breast cancer cells as experimental models, we observed a functional association between TGF‐β signaling and EGFR transactivation in breast cancer cell lines." (PMID 29215776, 2018). "The expression of EGFR in breast carcinoma is associated with greater tumor size, low cell differentiation and poorer prognosis." (PMID 29949609, 2018). "Here, we present a case of MPMT which have breast cancer and lung adenocarcinoma with heterogeneous epidermal growth factor receptor (EGFR) mutation status." (PMID 30453894, 2018). "EGFR is overexpressed in breast cancer tissues and is associated with higher aggressiveness and poor clinical outcomes." (PMID 29455658, 2018). "Amphiregulin (AREG), a ligand of the epidermal growth factor receptor, is not only essential for proper mammary ductal development, but also associated with breast cancer proliferation and growth." (PMID 30367629, 2018). "Breast cancers over-expressing the human epidermal growth factor receptors, HER1 (EGFR/c-erbB-1) or HER2 (neu-c-erbB-2), have been associated with disease progression, survival, stage and treatment response." (PMID 29439457, 2018). "Our hDiSNet provides the insights into human genetic disease and their associated proteins and mutations, such as the structural FGFR (EGFR)-MAPK pathway for interpreting the breast cancer and ErbB sub-network in brain cancer." (PMID 29560828, 2018). "Specifically, the amplification and mutation of EGFR proteins are shown to be driving events in basal-like breast cancers." (PMID 29983747, 2018). "Our results revealed that TGF‐β expression is positively correlated with EGFR expression in breast cancer tissues, and increased TGF‐β and EGFR levels are associated with the poor prognosis of patients with breast cancer." (PMID 29215776, 2018). "The EGFR increases angiogenesis and metastasis and is associated with poor clinical outcomes in breast cancer patients." (PMID 30373614, 2018). "There is also a strong association between nuclear STAT3 and EGFR expression in breast cancer samples and this EGFR/STAT3 relationship enhances tumorigenesis." (PMID 29262529, 2017). "Our combination of approaches to probe association between gangliosides and GFRs (co-IP, IF, immunogold-TEM, and PLA) provides novel and consistent evidence for strong GD3/EGFR association in breast CSCs and breast cancer cell lines." (PMID 28537895, 2017). "Differential expression in the metastatic sublines compared to parental MDA-MB-231 cells suggest a potential relevance of PTEN loss and EGFR overexpression in breast cancer metastasis." (PMID 28008153, 2017). "Recently, FAM83A has been found to be a key mediator of resistance to many EGFR tyrosine-kinase inhibitors in breast cancer by causing phosphorylation of c-RAF and PI3K p85, thus promoting proliferation of and invasion by breast cancer cells." (PMID 28641578, 2017). "WT161 and its chemical derivative MAZ1793 induce a decetylase-independent anti-proliferative effect on breast cancer cells, associated with downregulation of EGFR, Her2, and ERα." (PMID 29113288, 2017). "Of the cancer-associated biomarkers we have measured, the National Cancer Institute has approved only four for routine clinical use in the context of breast cancer: mutations in EGFR, HER2/neu gene overexpression, as well as uPA and PAI-1." (PMID 27525640, 2017). "Here, analysing genome-wide chromatin associations, the authors show that in breast cancer cells ZNF516 represses EGFR transcription through the interaction with the CtBP/LSD1/CoREST complex." (PMID 28947780, 2017).
breast carcinoma (continued). "Overexpression of epidermal growth factor receptor in breast cancer is associated with estrogen receptor negativity, higher histological grade and larger tumors." (PMID 29229933, 2017). "Currently, the amplification or mutation of EGFR has been found in human solid tumors, such as glioma, lung cancer, ovarian cancer, and breast cancer." (PMID 28630865, 2017). "Clinical studies in breast cancer suggest important associations between intratumoral hypoxia, the upregulation of epidermal growth factor receptor (EGFR or HER1), hypoxia-inducible factor 1α (HIF-1α), and reduced patient survival." (PMID 28038470, 2017). "It has also been shown that lapatinib-induced inhibition of the crosstalk between EGFR/ErbB2 and ER pathways in ErbB2+/ER+ breast cancers is closely linked to its anti-tumor efficacy." (PMID 28938602, 2017). "Epidermal growth factor receptor (EGFR) is well-studied in breast cancer with high activation of this pathway associated with poor patient outcome." (PMID 28327201, 2017). "We further demonstrated that iNOS was associated with EGFR phosphorylation, basal-like transcription patterns, and predicted poor outcome in patients with basal-like breast cancer (n=41)." (PMID 29113326, 2017). "The involvement of Jab1 in breast cancer is linked to the ER, EGFR and HER2 pathways by mediating downstream signalling that contributes to the tumour progression." (PMID 29228627, 2017). "EGFR is overexpressed in all subtypes of breast cancer, but is more frequently associated with aggressive TNBC and inflammatory breast tumors." (PMID 28532474, 2017). "Our observations confirm previous report on MDA-MB-468, a breast cancer cell line with elevated EGFR expression and mutation in PTEN gene." (PMID 27153109, 2016). "Epidermal growth factor receptor (EGFR) is commonly overexpressed in breast cancer and is associated with poor clinical outcomes; however, an increasing number of patients have shown a poor effective response to EGFR tyrosine kinase inhibitors (EGFR-TKI)." (PMID 27590506, 2016). "In fact, mutations of EGFR, Ras, and Raf are related to epithelial mesenchymal transition, migration, and tumor invasion of breast cancers, and furthermore MEK mutation was observed in malignant melanoma." (PMID 27902699, 2016). "HIF1α and HIF2α are implicated in therapeutic resistance in breast cancer, and HIF2α influences EGFR translation at hypoxia." (PMID 26849233, 2016). "EGFR mutations are indeed major drivers of cancer progression, and ErbB2 amplification is a common oncogenic event in breast cancer." (PMID 27351228, 2016). "The eleven lines tested included triple negative and Her2 positive breast cancers of grade 2 or higher, and we observed that Llgl1 loss was associated with increased EGFR expression." (PMID 27542214, 2016). "TOB1 is regulated by EGF-Dependent HER2 and EGFR signaling and TOB1 protein expression and phosphorylation is associated with EGF-dependent erbB signaling and proliferation in breast cancer." (PMID 27506935, 2016). "Aberrant EGF and its receptor EGFR (ErbB-1) signaling has been extensively described as a major cause of progression and metastasis of breast cancer." (PMID 27829223, 2016). "It was worth mentioning that hyperactivation of ERK1/2/MAPK signaling occurring downstream of EGFR or HER2 in breast cancer can induce loss of ER expression leading to establishment of ER-negative phenotype." (PMID 26918448, 2016). "HER-2/neu is a member of the epidermal growth factor receptor (HER/EGFR/ERBB) family, whose amplification in breast cancer is associated with increased aggressiveness, therefore becoming an important target of therapy for about 20%–30% of patients." (PMID 28536377, 2016). "Further, it has been shown to co-localize with HER2, a known EGFR protein associated with more aggressive breast cancers." (PMID 27241529, 2016).
breast carcinoma (continued). "Overcoming antiestrogen resistance is, therefore, a priority for breast cancer researchers, and a number of factors have been implicated in endocrine resistance including EGFR and HIF-1." (PMID 26849233, 2016). "Tumor-associated fatty acid synthase (FAS) is implicated in breast carcinoma and is connected to the epidermal growth factor receptor (EGFR) signaling pathway." (PMID 27483305, 2016). "In contrast, when the HER2-positive BT474 breast cancer cell line was employed in the same experiment, EGFR was barely detectable in association with CDCP1, but HER2 robustly associated with a mimetic of the cleaved form of CDCP1 (ΔCDCP1)." (PMID 27495374, 2016). "Correlation analysis demonstrated a positive and significant correlation between PMCA2 and the Basal marker EGFR across all breast cancers, however, within the Basal subtype this association was negative." (PMID 27148852, 2016). "There is increasing evidence becoming available showing that breast cancer progression is associated with a defect in EGFR endocytosis." (PMID 27142862, 2016). "In summary, inhibition of components of the PI3K/Akt/GSK3/mTOR in EGFR-overexpressing MDA-MB 468 breast cancer and HCT8 colon cancer cell lines is associated with inhibitor-specific changes in PCho content." (PMID 27811956, 2016). "More recently PIK3CA mutations have been shown to induce tumor heterogeneity and are associated with activation of EGFR-signaling and reduced relapse free survival in basal subtype of breast cancer." (PMID 27941987, 2016). "In canine mammary cancer there is only one study suggesting that concurrent COX-2/EGFR positive immunoexpression is associated with higher number of intratumoral CD3+ T-lymphocytes." (PMID 28053982, 2016). "In the past few years, new evidence has emerged that EGFR is specifically important for IBC, as EGFR is overexpressed and is a predictor of poor prognosis and worse overall survival and risk of recurrence in this aggressive form of breast cancer." (PMID 25887413, 2015). "For example, amplification of HER2, a human epidermal growth factor receptor, occurs in ~20% of breast cancers and is associated with a more aggressive disease." (PMID 26181331, 2015). "Several investigators have studied the EGFR-mutational status in breast cancer patients from different global regions with variable results." (PMID 26267891, 2015). "The findings of this study suggest that while EGFR activating mutations are relevant to understanding the etiology and progression of breast cancer, they are insufficient to drive chemotherapeutic resistance." (PMID 25969993, 2015). "Amplification of epidermal growth factor receptor (EGFR) occurs in ~50% of basal-like breast cancer, and mutations in the epidermal growth factor receptor (EGFR) have been reported in up to ~ 10% of Asian TNBC patients." (PMID 25969993, 2015). "Under hypoxia, phosphorylation of Tyr393 by EGFR enhances cell survival and invasiveness and this was associated with poor prognosis of breast cancer patients." (PMID 26287249, 2015). "Previously, inhibition of PKCζ has been linked to EGFR-induced chemotactic migration of breast cancer cells." (PMID 26218882, 2015). "In breast cancer, EGFR overexpression is associated with large tumor size, EMT, metastasis and poor clinical outcomes." (PMID 26025929, 2015). "Very recently, zoledronic acid was proven to enhance the effect of EGFR-inhibitors and even to overcome resistance acquired through the gatekeeper mutation T790M in non-small cell lung cancer, breast cancer and colorectal cancer." (PMID 25646931, 2015). "Because EGFR-ER interaction is associated with TAM resistance in breast cancer and EGFR/ER signal cross-talk is bidirectional, we next tested if PTPH1 enhances the TKI-induced growth-inhibition by disrupting the EGFR-ER complex." (PMID 26079946, 2015). "Taken together, these results strongly indicate that elevated expression of Anxa2 and EGFR has a direct association with EMT in breast cancer." (PMID 26307676, 2015).